PPARA (peroxisome proliferator activated receptor alpha)
Diseases named in the same sentence as PPARA in open-access papers (continued):
Sharing a sentence is not in itself a finding about the gene and the disease.
glioma (55 papers, 2010 to 2025). A benign or malignant brain and spinal cord tumor that arises from glial cells (astrocytes, oligodendrocytes, ependymal cells). "More recently, hyperactivation of HOTAIR in glioma pathogeneses has been shown to be associated with histone H3K27-methylation-mediated transcriptional repression of peroxisome proliferator-activated receptor alpha (PPARα)." (PMID 38366205, 2024). "Although fenofibrate-induced peroxisome proliferator-activated receptor alpha (PPARα) transcription activation has been shown to play an important role in the malignant progression of gliomas, the underlying mechanisms are poorly understood." (PMID 34082742, 2021). "Bioinformatics analysis showed that Peroxisome proliferator-activated receptor alpha (PPARα) is another target of miR-19a, and a low PPARα expression level is associated with worse outcomes in clinical glioma patients." (PMID 30583549, 2018). "In this study, we used bioinformatic and integrative analytical approaches to detect the underlying function and molecular mechanism of PPARα in glioma." (PMID 27835866, 2016). "A recent study showed that fenofibrate by activating the PPARα/FoxO1/p27kip pathway could actually induce the death of human U87MG glioma cells, causing cell cycle arrest in the G0/G1 phase." (PMID 35203272, 2022). "We found that PPARα is associated with glioma grade and GBM survival." (PMID 27835866, 2016). "In fact, knockdown of PPARA in human glioma stem cells not only reduced in vitro proliferation but also inhibited orthotopic xenograft tumor growth, suggesting a role in tumor initiation." (PMID 41148824, 2025). "A different study using bioinformatics analysis reported that the peroxisome proliferator-activated receptor alpha (PPARα) acts as a target for miR-19a, among the worse outcomes in clinical glioma patients." (PMID 37444408, 2023). "In contrast, PPARα is highly expressed in glioblastoma and glioma stem cells, and its inhibition results in the downregulation of key regulators of fatty-acid oxygenation, ACOX1 and CPT1A, and reduced tumor growth in mice." (PMID 35954274, 2022). "Fenofibrate, a PPARα agonist, can inhibit the growth of gliomas, while NF-κB modulates tumor formation and progression by inducing the expression of oncogenes involved in proliferation, survival, angiogenesis, and metastasis." (PMID 36045714, 2022). "In human glioma cells, another study showed that PPARα upregulated miR-214 expression, resulting in E2F2 mRNA decay and inhibition of cell proliferation." (PMID 36507526, 2022). "ROS accumulation and IGF-IR inhibition contribute to fenofibrate/PPARα-mediated inhibition of glioma cell motility in vitro." (PMID 35980268, 2022). "High PPARα expression has been described in glioma stem cells compared to fetal neuronal stem cells." (PMID 35954274, 2022). "Conversion of glycolysis to fatty acid oxidation by activating PPARα eventually led to the depletion of ATP in glioma cells." (PMID 34211978, 2021). "Through immunohistochemical staining of clinical samples, it was shown that with increasing glioma grade, the expression level of PPARα decreased significantly." (PMID 34082742, 2021). "By comparing the expression levels of HOTAIR and PPARα in low-grade gliomas and glioblastomas, it was found that the expression of HOTAIR in GBM was upregulated, while PPARα was expressed at low levels." (PMID 34082742, 2021). "PPARα activator fenofibrate also inhibited glioma growth by inducing the dependence of tumor cells on fatty acid oxidation instead of glycolysis." (PMID 34211978, 2021). "For the first time, it was shown that after knockdown of the expression of HOTAIR in gliomas, the expression of PPARα was significantly upregulated, and the invasion and proliferation ability of gliomas were obviously inhibited." (PMID 34082742, 2021). "Taken S that PPARα inhibition of glioma cell growth is mediated by the sequential effects on miR-214 transcription and E2F2 expression." (PMID 29862267, 2018).
glioma (continued). "We found that PPARα expression is low in glioma tissue compared with normal brain tissue and that overexpression of PPARα in glioma cell lines inhibits their proliferation." (PMID 29862267, 2018). "Anaplastic gliomas and glioblastoma multiforme (GBM) tissue expressed lower levels of PPARα compared with low-grade gliomas tissue, and expression in gliomas decreased with increasing tumor grade." (PMID 29862267, 2018). "Our results thus suggest that PPARα inhibits human glioma cell proliferation through a miR-214- and E2F2-dependent pathway and identify novel potential molecular targets for the treatment of human gliomas." (PMID 29862267, 2018). "Collectively, these data uncover a novel role for a PPARα-miR-214-E2F2 pathway in controlling glioma cell proliferation." (PMID 29862267, 2018). "Analysis of patient samples from the CGGA database showed that expression of PPARα is low in glioma tissues and that the expression correlated with patient prognosis." (PMID 29862267, 2018). "Collectively, our findings suggest that PPARα plays an important role in the proliferation of human glioma cells." (PMID 29862267, 2018). "Our data suggest that PPARα expression correlates with the prognosis of glioma patients and inhibits the proliferation of human glioma cells by regulating DNMO3os transcription." (PMID 29862267, 2018). "Overexpression of PPARα in glioma cells promoted transcription of DNMO3os, leading to increased expression of miR-214." (PMID 29862267, 2018). "Here, we show that PPARα is expressed at lower levels in anaplastic gliomas and glioblastoma multiforme (GBM) tissue compared with low-grade gliomas tissue, and low expression is associated with poor patient prognosis." (PMID 29862267, 2018). "Here, we found that the proliferation of human glioma cells is inhibited by PPARα overexpression, which promotes transcription of DNMO3os, thereby increasing miR-214 levels and consequently decreasing translation of its target E2F2 mRNA." (PMID 29862267, 2018). "To analyze the functional role of PPARα in human glioma, we overexpressed PPARα in two human glioma cell lines, U87 and U251, using lentiviral vectors." (PMID 29862267, 2018). "Fenofibrate, a PPARα agonist which drives transcriptional activity, has been shown to reduce cancer cell growth in U-87-MG glioma cells and in other cancers." (PMID 28491867, 2017). "PPARα agonism or overexpression inhibited glioma cell proliferation, invasion, and aerobic glycolysis as well as suppressed glioma growth in an orthotopic model." (PMID 27835866, 2016). "In the current study, PPARα has been identified as a critical marker not only of tumor grade but also for prognosis in glioma." (PMID 27835866, 2016). "PPARα expression was measured in 5 normal brain tissues and 20 glioma tissues using qRT-PCR and a similar trend of low expression of PPARα in glioma tissues was observed." (PMID 27835866, 2016). "Western blot analysis showed that PPARα expression was increased in glioma cells with down-regulation of miR-19a." (PMID 27835866, 2016). "To our knowledge, we are the first to propose that the E2F1/miR-19a/PPARα feedback loop is a key regulatory element in glioma." (PMID 27835866, 2016). "This study explores the clinical features, biological functions and potential mechanisms of action of PPARα in glioma both in vitro and in vivo." (PMID 27835866, 2016). "We determined the direct interaction between miR-19a and its binding site within PPARα mRNA, usingluciferase reporter constructs containing either wild-type (pGL3-WT- PPARα-3′UTR) or mutant (pGL3-MUT- PPARα-3′UTR) PPARα 3′UTRs transfected into glioma cells." (PMID 27835866, 2016). "We used bioinformatic analysis, TargetScan and PicTar, to investigate the upstream of PPARα in glioma cells." (PMID 27835866, 2016). "To further investigate the role of PPARα in tumor growth of glioma in vivo, we extended our investigation by intracranial implantation of PPARα overexpressing U87 cells in nude mice." (PMID 27835866, 2016).
glioma (continued). "The depletion of E2F1/miR-19a signaling inhibited glioma cell proliferation, invasion and aerobic glycolysis accompanying the downregulation of PPARα." (PMID 27835866, 2016). "PPARα expression was significant lower in high grade gliomas (HGG) compared to low grade gliomas (LGG)." (PMID 27835866, 2016). "PPARα inhibits glioma cell proliferation, invasion, and aerobic glycolysis, and suppresses glioma growth in an orthotopic model via a positive feedback loop with E2F1 and miRNA-19a." (PMID 27835866, 2016). "Two employed two independent glioma gene expression data sets (Rembrandt data and GSE4290 data) were uesd to examine the association between PPARα expression levels and glioma grade." (PMID 27835866, 2016). "PPARα expression was analyzed in whole genome gene profiling of 158 glioma tissues based on Chinese Glioma Genome Atlas (CGGA) data." (PMID 27835866, 2016). "Our results show that PPARα is an important factor for malignant progression survival in glioma patients and exhibits antitumor effects by reducing cell proliferation, invasion and aerobic glycolysis." (PMID 27835866, 2016). "E2F1 and miR-19a expression were markedly decreased following up-regulation of PPARα in a nude mouse glioma xenograft model." (PMID 27835866, 2016). "In this study, we found that PPARα expression was lower in high grade gliomas and PPARα was an independent prognostic factor in GBM patients." (PMID 27835866, 2016). "Here we demonstrate that IGF-I-induced and serum-induced motility of Glioma cell lines were both severely attenuated by fenofibrate, which depended, at least partially, on the activation of PPARα." (PMID 20569465, 2010). "Our presented work is an in vitro study in which we evaluate the involvement of IGF-IR and ROS in fenofibrate/PPARα -mediated inhibition of Glioma cell motility." (PMID 20569465, 2010). "Since the Glioma cell lines used in this study show much higher levels of PPARα expression than control astrocytes, PPARα driven UCP2 expression is not unlikely." (PMID 20569465, 2010). "This 2.7-fold increase in nuclear PPARα was accompanied by almost 4-fold increase in PPAR-transcriptional activity, further supporting the possibility of using fenofibrate to trigger PPARα-mediated responses in Glioma cells." (PMID 20569465, 2010). "All five human Glioma cell lines demonstrated elevated PPARα protein levels in comparison to human fetal astrocytes." (PMID 20569465, 2010). "Further experiments revealed that PPARα-dependent accumulation of ROS is a strong contributing factor in Glioma cell lines responses to fenofibrate." (PMID 20569465, 2010). "We further examined the expression of HOTAIR and PPARα in gliomas." (PMID 34082742, 2021). "Fenofibrate, as a PPARα agonist, can inhibit the growth of gliomas in animal models of gliomas." (PMID 34082742, 2021). "PPARα inhibited growth of glioma cells through the E2F1/miR-19a feedback loop." (PMID 33381564, 2020). "Here, we investigated the function of PPARα in human glioma cells." (PMID 29862267, 2018). "Thus, PPARα overexpression appears to inhibit glioma cell proliferation by inducing G0/G1 phase arrest." (PMID 29862267, 2018). "PPARα is down-regulated by E2F1/miR-19a signaling in glioma cells." (PMID 30583549, 2018). "To determine whether PPARα-mediated transcription of miR-214 is involved in the reduced proliferation of PPARα-overexpressing human glioma cells, we first investigated the effect of lentiviral-mediated overexpression of miR-214." (PMID 29862267, 2018). "PPARα overexpression inhibits growth, invasion, and aerobic glycolysis in glioma cells." (PMID 28491867, 2017). "Overall, these data suggest that PPARα inactivation may play an important role in glioma development and survival prediction." (PMID 27835866, 2016).
glioma (continued). "PPARα inhibited the malignant progression of glioma in vivo and in vitro." (PMID 27835866, 2016). "We verifed the inhibitory effect of PPARa on glioma cells by adding fenofibrate to our cultures." (PMID 27835866, 2016). "Si-PPARα abolished the role of fenofibrate indicating PPARα may affect cellular behavior in glioma by inhibiting the phosphorylation status of Akt and Erk1/2." (PMID 27835866, 2016). "To verify whether fenofibrate-mediated ROS accumulation and inhibition of Glioma cell motility depends on PPARα, we have utilized PPARα siRNA." (PMID 20569465, 2010). "Furthermore, PPARα agonists (gemfibrozil and Wy14643) activated PPARα, inducing autophagy in U251 human glioma cells stably expressing human APP and human microglia (HM) cells, which reduced amyloid pathological changes and reversed anxiety symptoms and memory impairment in mice." (PMID 38004166, 2023). "However, the overexpression of PPARα in glioma stem cells (GSCs) has been observed." (PMID 35954274, 2022). "Here, we asked whether and how PPARα might participate in the development of glioma." (PMID 29862267, 2018). "Thus, we have elucidated a PPARα-miR-214-E2F2 signaling pathway in human glioma cells." (PMID 29862267, 2018). "Thus, PPARα is a potential prognostic biomarker in human glioma." (PMID 29862267, 2018). "Moreover, overexpression of PPARα markablely prolonged the survival time of glioma-bearing mice." (PMID 27835866, 2016). "This information was used for design of a combinatorial therapeutic strategy of fenofibrate-mediated PPARα activation and siRNA-mediated HOTAIR repression to robustly retard glioma proliferation and invasion." (PMID 38366205, 2024). "The study revealed that pharmacologically activating PPARA with the agonists gemfibrozil and Wy14643 induces autophagy in human microglia cells and U251 human glioma cells expressing the human APP mutant (APP-p.M671L), and this induction is PPARA-dependent." (PMID 38259497, 2023). "Our results suggest that HOTAIR can negatively regulate the expression of PPARα and that the combination of fenofibrate and si-HOTAIR treatment can significantly inhibit the progression of gliomas." (PMID 34082742, 2021). "Then, glioma cells were treated with both the PPARα agonist fenofibrate and si-HOTAIR, and the results showed that the proliferation and invasion of glioma cells were significantly inhibited." (PMID 34082742, 2021). "Our study not only explores the molecular mechanism by which HOTAIR regulates PPARα but also verifies the therapeutic effect of the combined application of the PPARα agonist fenofibrate and siRNA HOTAIR on glioma through in vivo animal experiments." (PMID 34082742, 2021). "Related studies have found that PPARα promoted the transcription of the DNMO3 complementary strand, which we also observed here in human glioma cell lines." (PMID 29862267, 2018). "Overexpression of PPARα in both U87 and LN229 glioma cells with low endogenous PPARα expression inhibited cell colony formation, invasion, and glucose consumption." (PMID 27835866, 2016). "We also evaluated PPARα, RelA, PKM1/2 and hnRNPs protein expression by Immunohistochemical (IHC) staining in a nude mouse glioma xenograft model to study the correlation among them." (PMID 26172294, 2015). "The effects of fenofibrate on Glioma cell motility, IGF-I receptor (IGF-IR) signaling, PPARα activity, reactive oxygen species (ROS) metabolism, mitochondrial potential, and ATP production were analyzed in human glioma cell lines." (PMID 20569465, 2010). "Therefore, we predicted that HOTAIR can reduce the expression of PPARα through the PRC2 protein, thereby promoting the malignant progression of glioma." (PMID 34082742, 2021). "Having shown that PPARα promotes miR-214 transcription and that miR-214 overexpression reduces E2F2 protein levels in glioma cells, we next asked whether the inhibitory effects of PPARα on proliferation were mediated through miR-214 and E2F2." (PMID 29862267, 2018).
glioma (continued). "Although PPARα and PPARγ bind to the same cofactors, they appear to have differential effects on gene transcription in glioma cells; the role of PPARβ in glioma has not been characterized." (PMID 28491867, 2017). "PPARα expression is lower in high-grade gliomas compared with normal brain tissue; signifying worse prognosis in GBM patients." (PMID 28491867, 2017). "Then, we explored the molecular mechanism by which lncRNA HOTAIR regulates PPARα in cell lines in vitro and in a nude mouse glioma model in vivo and explored the effect of the combined application of HOTAIR knockdown and fenofibrate treatment on glioma invasion." (PMID 34082742, 2021). "Importantly, glioma cell proliferation and E2F2 protein expression were both increased in PPARα-overexpressing cells infected with AS-miR-214 compared with PPARα sequence." (PMID 29862267, 2018). "However, there have been no studies of PPARα in human gliomas." (PMID 29862267, 2018). "Our results indicate that although fenofibrate-mediated inhibition of the IGF-IR may not be sufficient in counteracting Glioma cell dispersal, PPARα-dependent metabolic switch and the resulting ROS accumulation strongly contribute to the inhibition of these devastating brain tumor cells." (PMID 20569465, 2010).
bladder cancer (54 papers, 2006 to 2026). "PPARA has been demonstrated to be associated with glucose metabolic reprogramming in glioblastoma, bladder cancer and lung cancer." (PMID 40693878, 2025). "The expression of PPARα mRNA was previously correlated with liver and bladder cancers in rodents 38,39." (PMID 30555653, 2018). "Bilirubin may offer a therapeutic potential because it activates PPARα and suppresses PPARγ, and fenofibrate has not been associated with bladder cancer." (PMID 28348577, 2017). "Increased NCOR1 and NCOR2/SMRT expression occurs also in breast and bladder cancer and suppressed the responsiveness of nuclear receptors that exert mitotic restraint, such as VDR and PPARα,γ." (PMID 23098689, 2013). "Also in a bladder cancer cell line, VEGF expression was upregulated in response to stimulation with PPARα, PPARβ/δ, and PPARγ agonists, while another bladder cancer cell line responded only to PPARβ/δ activation." (PMID 32785018, 2020). "Our study is supported by another in genitourinary cancers comparing mRNA and miRNA profiling, which showed evidenced of an enriched PPARα pathway in RCC but not in bladder cancer." (PMID 23951092, 2013). "For cancer therapies, the use of PPAR agonists is more debated, in particular for PPARα, which induces liver and bladder cancers in mice, but apparently not in humans." (PMID 23024649, 2012). "Importantly, the fenofibrates that are PPARα agonists have not been shown to induce bladder cancer." (PMID 28348577, 2017).